FAM3D (FAM3 metabolism regulating signaling molecule D)
Synonyms: EF7; OIT1
Tractability: Antibody: UniProt places it where antibodies can reach, with high confidence; UniProt predicts a signal peptide or a membrane-spanning region; its Gene Ontology location is reachable by antibodies, with medium confidence. PROTAC: ubiquitination databases record sites on it.
Gene: Protein-coding gene on chromosome 3 (58,633,941 to 58,666,877, reverse strand). Ensembl gene ENSG00000198643.
Subcellular location: Secreted
Gene Ontology:
Molecular function: protein binding; cytokine activity
Biological process: negative regulation of insulin secretion; signal transduction
Cellular component: extracellular region
Genetic constraint (gnomAD): Loss-of-function variants: 28 observed, 34.02 expected, observed/expected ratio (o/e) 0.82, 90% interval 0.61 to 1.13. The upper end of that interval is the gene's LOEUF score, 1.13, which puts it in group 4 of 6, group 1 being the genes least tolerant of losing a copy. Missense variants: 253 observed, 306.38 expected, observed/expected ratio (o/e) 0.83, 90% interval 0.74 to 0.92. Synonymous variants: 115 observed, 107.88 expected, observed/expected ratio (o/e) 1.07, 90% interval 0.92 to 1.25.
Homologues: Orthologues: chimpanzee FAM3D (100% identical), macaque FAM3D (89% identical), dog FAM3D (80% identical), rabbit FAM3D (74% identical), guinea pig FAM3D (72% identical), mouse Fam3d (71% identical), rat Fam3d (55% identical), tropical clawed frog fam3d (52% identical), Caenorhabditis elegans famp-1 (36% identical). Paralogues in human: FAM3A (55% identical), FAM3C (50% identical), FAM3B (32% identical).
Diseases named in the same sentence as FAM3D in open-access papers:
FAM3D is named in the same sentence as 36 diseases in open-access papers, as found by Europe PMC text mining. Sharing a sentence is not in itself a finding about the gene and the disease. The quoted sentences say what the papers report.
colon cancer (6 papers, 2016 to 2024). "FAM3D deficiency can promote the incidence and development of colon cancer." (PMID 36510584, 2022). "Furthermore, according to the CPTAC database, FAM3D protein level was significantly reduced in colon cancer (COAD) tissues." (PMID 39388305, 2024). "We then examined the potential clinical relevance of FAM3D to human colon cancer progression." (PMID 33219235, 2020). "FAM3D could inhibit colon cancer development by NF-κB signaling pathway." (PMID 37031243, 2023). "FAM3D belongs to the family with the sequence similarity 3 (FAM3) gene family, and it is overexpressed in colon cancer." (PMID 33564686, 2021).
colitis (4 papers, 2020 to 2023). Inflammation of the colon. "Here, by using gene deficient mice, the authors show that Fam3D is critically involved in colon homeostasis, host defense against colitis-associated carcinogenesis, and the balance of microbiota." (PMID 33219235, 2020). "After 3-month of separation, WT and Fam3D−/− mice resumed colitis phenotype similar to the characteristics before co-housing, suggesting that alteration of microbiota in the colon is a result of Fam3D deficiency." (PMID 33219235, 2020). "Pretreatment of Fam3D−/− mice with antibiotics significantly reduces the severity of chemically induced colitis and wild type (WT) mice co-housed with Fam3D−/− mice phenocopy Fam3D-deficiency showing increased sensitivity to colitis and skewed composition of fecal microbiota." (PMID 33219235, 2020). "FAM3D represents a class of guardians of the gut; the deficiency in FAM3D is associated with impaired integrity of colonic mucosa, increased epithelial hyper‐proliferation, reduced antimicrobial peptide production, and increased sensitivity to chemically induced colitis." (PMID 40625576, 2023). "Here, we demonstrate that deficiency in Fam3D is associated with impaired integrity of colonic mucosa, increased epithelial hyper-proliferation, reduced anti-microbial peptide production and increased sensitivity to chemically induced colitis associated with high incidence of cancer." (PMID 33219235, 2020). "In DSS-induced colitis, Fam3D−/− mice showed markedly increased severity of inflammation including more rapid body weight loss, increased rectal bleeding, and diarrhea." (PMID 33219235, 2020). "Both WT and Fam3D−/− mice that received Adv-FAM3D demonstrated a significant improvement in the severity of colitis including body weight and colon length over the 7-day DSS treatment, in contrast to Adv-null treatment of mouse colon." (PMID 33219235, 2020). "FAM3D is upregulated in the colon of the dextran sulfate sodium-induced colitis mouse model." (PMID 37173923, 2023). "Therefore, Fam3D−/− mice are more highly sensitive to DSS-induced colitis indicating a critical role of Fam3D in protecting the colon from inflammatory insults." (PMID 33219235, 2020). "Histological analysis of colonic tissue from mice with 7-day DSS treatment infected with Adv-null demonstrated a marked colitis with a totally damaged mucosa and leukocyte infiltration, but treatment with Adv-FAM3D showed a significant restoration from colitis in both WT and Fam3D−/− mice." (PMID 33219235, 2020). "Therefore, the increased levels of PBLD, FAM3D, KRT8, SULT2B1, GPA33, DEPTOR, and decreased expression of ACSL4, IFITM1 and HSD11B1 caused by mEVs has been demonstrated to attenuate colitis, implying that consumption of mEVs has the potential to improve intestinal health." (PMID 35893911, 2022).
abdominal aortic aneurysm (1 paper, 2025). Enlargement and ballooning of the vessel that supplies arterial blood to the abdomen, pelvis and legs. "FAM3D functions as a chemotactic agonist for the G protein-coupled receptors FPR1 and FPR2, strongly attracting immune cells such as neutrophils and monocytes, thereby contributing to the pathogenesis of abdominal aortic aneurysms." (PMID 41465269, 2025).
aneurysm (1 paper, 2020). Bulging or ballooning in an area of an artery secondary to arterial wall weakening. "He and colleagues found that FAM3D induced Mac-1-mediated neutrophil recruitment and aggravated aneurysm formation through formyl peptide receptor-related Gi protein and β-arrestin signaling." (PMID 32968712, 2020).
colorectal adenoma (1 paper, 2023). An adenoma that arises from the colon or rectum. "Whether TXA2 regulates FAM3D expression in colorectal adenomas is unknown and deserves further investigation." (PMID 37173923, 2023).
diffuse large B-cell lymphoma (1 paper, 2024). "As another example, patients with low-grade glioma, melanoma, and diffuse large B-cell lymphoma with high FAM3D expression have worse prognosis." (PMID 39388305, 2024).
endometrial cancer (1 paper, 2024). Primary or metastatic malignant neoplasm involving the endometrium (mucous membrane that lines the endometrial cavity). "For example, FAM3D expression increases in endometrial cancer tissues compared to normal tissues." (PMID 39388305, 2024).
infertile (1 paper, 2015). "Furthermore, a secretory protein that belongs to family with sequence similarity 3, member D (FAM3D) is uniquely expressed in fertile donors and absent in all the three infertile groups." (PMID 26321892, 2015). "Similarly, the protein FAM3D (Q96BQ1) was uniquely expressed in the fertile control group and not identified in any of the infertile group." (PMID 26321892, 2015).
lymph node metastasis (1 paper, 2022). "It was discovered that the level of FAM3D expression in HNSCC tissues was highly linked with clinicopathological characteristics such as T grade, stage, and lymph node metastasis." (PMID 36510584, 2022).
male infertility (1 paper, 2015). The inability of the male to effect fertilization of an ovum after a specified period of unprotected intercourse. "MME and FAM3D along with ROS levels in the seminal plasma may serve as good markers for diagnosis of male infertility." (PMID 26321892, 2015).
type 2 diabetes (1 paper, 2025). "In this work, we identify key pathways (e.g., complement cascade), potential therapeutic targets (e.g., FAM3D in type 2 diabetes), and biomarkers of diabetic comorbidities (e.g., EFEMP1 and IGFBP2) through causal inference, pathway enrichment, and Cox regression of clinical trial outcomes." (PMID 40032831, 2025).
cancer (13 papers, 2016 to 2025). A tumor composed of atypical neoplastic, often pleomorphic cells that invade other tissues. "FAM3D expression were found to be positively correlated with immune infiltrating cells, such as cancer-associated fibroblasts, myeloid-derived suppressor cells, macrophage cells, T cell CD8+ cells, regulatory T cells, and T cell follicular helper cells." (PMID 36510584, 2022). "However, FAM3D is upregulated in some cancers and is linked to a bad prognosis." (PMID 39388305, 2024). "In the colon, FAM3D plays a role in homeostasis, protection against inflammation-related cancers, and maintenance of normal gut microbiota composition." (PMID 41465269, 2025). "As a cytokine-like gene, FAM3 family includes FAM3A, FAM3B, FAM3C, and FAM3D, and is involved in the occurrence and development of several cancers." (PMID 37056931, 2023). "FAM3D expression was significantly higher in C2 and C3 subtypes than in C4 and C6 subtypes in pan-cancer and BRCA, which implied that the higher FAM3D expression in tumor tissues the better prognosis of patients." (PMID 37704682, 2023). "Muc4 maintains the intestinal homeostasis by upregulation of Muc2 and Fam3D (guardians of the gut) and downregulation of cancer-promoting mucin (Muc13)." (PMID 35255004, 2022). "FAM3D protein was more poorly expressed in higher stages of CRCs, with the lowest level in stage IV cancers." (PMID 33219235, 2020). "Moreover, SESN2 knockdown weakened the tumor suppressor effect of FAM3D KO, but SESN2 overexpression reduced the cancer-promoting effect of FAM3D overexpression." (PMID 39388305, 2024). "Considering the important role of FAM3D in maintaining intestinal homeostasis, preventing inflammation-related carcinogenesis, and inhibiting cancer cell proliferation and migration, it is of great significance to study its specific functions and mechanisms in CRC." (PMID 39388305, 2024). "Similarly, compared with adjacent cancer tissues, the expression of FAM3D was dramatically downregulated in CRC tissues, and FAM3D protein gradually decreased with increasing tumor stage." (PMID 39388305, 2024). "FAM3B expression was positively correlated with FAM3D expression in pan-cancer (Cor = 0.41)." (PMID 37704682, 2023). "Therefore, FAM3D is vital in gastrointestinal homeostasis, protection against inflammation-related cancers, and normal microbiota composition." (PMID 36510584, 2022). "Therefore, FAM3D (Fam3D) represents an anti-cancer molecule in both human and mice." (PMID 33219235, 2020). "FAM3A expression was positively correlated with FAM3D, and FAM3B expression in pan-cancer (Cor = 0.10, and 0.13)." (PMID 37704682, 2023). "Most of the genes showed an increase in gene expression during the stages of cancer, particularly in the last two stages, except for NDRG2, FAM3D, KRT78, SLURP1, MUC21, and CRCT1, which showed a significant drop in gene expression compared to normal tissue." (PMID 37917867, 2023). "UPK3A, FAM3D, and LCN2, which participate cancer cell metabolisim, were also downregulated in all PDOs after CUL4B ablation." (PMID 32054830, 2020). "Seven genes were expressed in non-cancerous tissues only, including LINC01612 (TSG), FAM3D (inflammation), HCN1, and CNBD1 (mutation in cancer) and three other genes." (PMID 37509325, 2023). "Additionally, because CRC is a highly heterogeneous cancer, different CRC cell lines and different tumor microenvironments may respond differently to FAM3D." (PMID 39388305, 2024).
tumor (8 papers, 2016 to 2026). "Therefore, it is valuable to explore the association between the expression level of FAM3D and its impacts on the prognosis and tumor microenvironment in HNSCC." (PMID 36510584, 2022). "In addition, in many tumor types, increased FAM3D expression is linked to a favorable prognosis." (PMID 39388305, 2024). "The results found that FAM3D deletion resulted in a reduction in tumor size and weight, while high expression of FAM3D led to an increase in both parameters." (PMID 39388305, 2024). "There exists a robust correlation between FAM3D expression and tumor cell sensitivity to a variety of drugs such as elismore and lincitinib." (PMID 39388305, 2024). "In different datasets, FAM3D mRNA and protein levels were all significantly lower in HNSCC tissues than in normal tissues, and they were strongly inversely associated with tumor grade, stage, lymph node metastasis, and T stage." (PMID 36510584, 2022). "Our study explored the impact of FAM3D as a favorable prognostic marker for HNSCC on the tumor immune microenvironment from multiple perspectives." (PMID 36510584, 2022). "This study explores the role of FAM3D in the diagnosis, prognosis, and tumor microenvironment (TME) scores in HNSCC via extensive bioinformatic data, which was crucial for the further development of immunotherapy for HNSCC." (PMID 36510584, 2022). "The relationships between FAM3D expression and tumor microenvironment (TME) scores, immune checkpoints, and antitumor compound half-maximal inhibitory concentration predictions were also explored." (PMID 36510584, 2022). "The data demonstrated that FAM3D enhances CRC tumor growth in vivo." (PMID 39388305, 2024). "For example, FAM3D may exert an anti-tumor effect in the CRC microenvironment, whereas in CRC cells, it promotes proliferation and motility due to the influence of other signaling pathways or factors." (PMID 39388305, 2024). "One possible explanation was that FAM3D may exhibit different functions in the tumor microenvironment and the cell environment." (PMID 39388305, 2024). "Likewise, our study showed that the expression of FAM3D was significantly higher in normal colorectal tissues than in tumor tissues." (PMID 37704682, 2023). "This indicated that FAM3D may participate in the tumor genesis and progression by affecting the TME." (PMID 36510584, 2022). "Furthermore, the immunohistochemical results of FAM3D in HNSCC tumor tissues and normal tissues were examined from THPA." (PMID 36510584, 2022). "The convergence of tumor suppression (FHIT, FAM107A), metabolic reprogramming (PDHB), and immune/signaling (PTPRG, FAM3D) genes within a single genomic region suggests a potential resistance-associated haplotype block." (PMID 42302616, 2026). "The genes with low expression in the tumor group were CRISP3, FAM3D, SCNN1B, CRISP2, RBM20, PHYHIP, C2orf54, SLC5A1, PTCRA, C15orf59, and ANO10." (PMID 35389773, 2022). "Two potential targets of this asRNA, FAM3D and FAM107A, were also downregulated in TCGA tumours (77.1 and 25.8-fold, respectively)." (PMID 29263803, 2016). "In addition, our study also revealed that FAM3D was lowly expressed in BRCA, HNSC tumor tissues, and low FAM3D expression was negatively correlated with poor prognosis, implying that FAM3D exhibits anti-oncogene properties in BRCA and HNSC." (PMID 37704682, 2023). "Protein intensity of FAM3D in normal tissues was strong, while that in tumor tissues was negative or moderate." (PMID 36510584, 2022). "According to this study's findings, increased expression of FAM3D may limit macrophage and MDSC infiltration into the tumor's immune environment while promoting the infiltration of T cell CD8+ cells, Treg cells, and Tfh cells." (PMID 36510584, 2022). "Sixteen nearby genes showed higher expression in non-cancerous tissues, including seven with almost no expression in tumor (HCN1, SLC22A2, FAM3D, LRFN5, LINC01612, LINC02512, and CNBD1)." (PMID 37509325, 2023).
FAM3D also shares sentences with these, for which no sentence is quoted: colorectal cancer (2 papers); adenoma (1); aspergillosis (1); Barrett esophagus (1); cervical spondylosis (1); Chronic colitis (1); COVID-19 (1); dysplasia (1); fibrosarcoma (1); gastric cancer (1); glioma (1); head and neck squamous cell carcinoma (1); Hyperglycemia (1); Insulin resistance (1); lung carcinoma (1); melanoma (1); nasopharyngeal carcinoma (1); neuroblastoma (1); Obesity (1); oral disease (1); pouchitis (1); preeclampsia (1); Stroke (1).